IL17A (interleukin 17A)
Diseases named in the same sentence as IL17A in open-access papers (continued):
Sharing a sentence is not in itself a finding about the gene and the disease.
chlamydial infection (22 papers, 2012 to 2025). "IL17A is an immune marker for chlamydial pathogenesis in the koala; increased expression of IL17A in KoRV B positive koalas, and concurrent immune dysregulation, may explain the differences in susceptibility to chlamydial infection and severity of disease seen between individuals and populations." (PMID 27706211, 2016). "Further development of assays for markers identified to be important in chlamydial infection, but which remained below the limit of detection in our study, in particular IL-17A, should be addressed and included for future studies." (PMID 38538683, 2024). "Immunisation following a two-dose regimen stimulated both systemic IgG to MOMP and antigen-specific cellular responses dominated by IFN-γ and IL-17A production, immune response signatures shown previously to be protective against chlamydial disease in representative vaccine-challenge models." (PMID 40573962, 2025). "Moreover, an elevated IL-17A response has been observed in clinical chlamydial infection in mouse model." (PMID 27219467, 2016). "In addition to IFN-γ, IL-17A has been suggested as an important cytokine for chlamydial infection, both for protection, but potentially also in disease pathology." (PMID 27219467, 2016). "This is significant as previous studies have found that IL17A is an immune marker for chlamydial disease severity and pathogenesis in koalas and, in the murine model, the magnitude and duration of infection with C. muridarum is significantly decreased in the absence of IL17." (PMID 27706211, 2016). "Considering the importance of iNOS in controlling chlamydial infection, we hypothesized that IL-17A is involved in inhibition of intracellular Cm growth through enhancing iNOS expression and NO production." (PMID 22745717, 2012). "Therefore, an appropriate level of IL-17A production is important for host defense against chlamydial infection." (PMID 22745717, 2012). "Specifically, the role of IL-17A in human lung chlamydial infection remains unclear." (PMID 22745717, 2012). "The decreased expression of IFNγ could make KoRV infected koalas more susceptible to persistent chlamydial infection, and a decrease in IL17A could make them more susceptible to gram negative bacterial, fungal and mycobacterial infection; but more tolerant of chlamydial infection." (PMID 31371797, 2019). "Another pro-inflammatory cytokine, IL-17A, which is secreted by Th-17 CD4+ T cells, is involved in the host defense against microbial organisms, but its role in protecting ruminants from chlamydial infections is currently unknown." (PMID 40573940, 2025). "qPCR was used to examine mRNA expression for Th1 (IFNγ), Th2-promoting (IL6, IL10) and Th17 (IL17A) cytokines, along with CD4 and CD8 in whole blood of koalas (n = 74) from Mt Eccles and Raymond Island in Victoria, Australia, with and without natural chlamydial infection." (PMID 31371797, 2019).
liver cirrhosis (22 papers, 2013 to 2025). "Notably, there was also a moderate association between salt intake and the IL-17A–to–IL-10 production ratio, which could be of prognostic relevance in liver cirrhosis according to recent studies." (PMID 40705454, 2025). "IL-17A had been reported to be involved in vascular inflammation, induce endothelial cell activation, and further up-regulate endothelial TF expression in liver cirrhosis." (PMID 37063881, 2023). "Moreover, an increase of IL-17A was demonstrated to be related to liver cirrhosis and hepatocarcinoma, and high IL-17A in local tissues could induce chronic inflammatory and immunosuppressive environment." (PMID 35144643, 2022). "However, for chronic hepatitis B, is well known, that IL-17A is positively regulated in HBV-mediated inflammation and may be relevant for the development of liver cirrhosis and HCC." (PMID 33435966, 2021). "In contrast, BE from HBV-CLD patients (p = .004), especially those without liver cirrhosis (p = .003), significantly provoked the expansion of T helper 17 cells (Th17 (CD3+CD4+IL-17A+)) compared to HCs (Figure 6aand c)." (PMID 36519342, 2023). "Excitingly, IL-1R, IL-6, or IL-17A, but not IL12 deletion in dKO mice respectively partly prolonged the survival time of dKO mice which means that production of pro-inflammation cytokines is responsible for the nosogenesis, at least partly, of liver cirrhosis." (PMID 35354799, 2022).
pneumonitis (22 papers, 2012 to 2025). An inflammatory process affecting the lung parenchyma. "Excessive IL-17A due to Th17 responses eventually causes the development of pneumonitis and pulmonary fibrosis 3 weeks after infection, when lytic MHV-68 is no longer detectable." (PMID 34484223, 2021). "In addition, IFN-γ and IL-17A can automatically amplify Th1 and Th17 responses, thus achieving a positive feedback loop that maintains the autoimmune process and ultimately leads to immune checkpoint inhibitor-associated pneumonitis." (PMID 36944820, 2023). "Through careful sorting and literature review, we find crosstalk between pathogenic Th17/Th1 cells (i.e., Th17.1) and pro-inflammatory monocytes, and activation of Th17(/Th1)/IL-17A (/IFN-γ) pathways may play a key role in the pathogenesis of ICI-pneumonitis." (PMID 36944820, 2023). "Intriguingly, the effector cytokines IL-17A and IFN-γ of Th17 and Th1 cells were also found to be elevated in ICI-pneumonitis patients." (PMID 36944820, 2023). "The authors noted higher frequencies of Th1 and Th17 cells in blood that correlated positively with IL-17A (blood and BALF) and higher ratios of Th17 cells to Tregs during development of ICI-Pneumonitis." (PMID 34675810, 2021). "Plasma IL-17A levels in NSCLC patients, at similar concentrations observed in the current study, have been reported to correlate with pneumonitis onset in patients with Stage IIIB-IV NSCLC undergoing immunotherapy; however, a comparison to normal controls were not provided." (PMID 39329890, 2024). "These authors measured the levels of the counteracting cytokines IL-17A (pro-inflammatory) and IL-35 (immunosuppressive, produced by Tregs) in bronchoalveolar lavage fluid (BALF) from patients (n = 13) with NSCLC who were experiencing episodes of ICI-Pneumonitis." (PMID 34675810, 2021). "Although this work may not have confirmed a clear role for IL-17A, it became evident that in response to ICI treatment, patients that develop ICI-Pneumonitis recruit increased numbers of inflammatory cells to the lungs, while immunoregulatory populations decreased in number and potency." (PMID 34675810, 2021).
thyroiditis (22 papers, 2013 to 2026). Inflammation of the thyroid gland. "For example, blocking the IL-17A signaling pathway has been shown to alleviate thyroiditis in mouse models while preserving the anti-tumor effects of ICIs, as demonstrated by the use of anti-IL-17 monoclonal antibodies." (PMID 40535343, 2025). "Our previous study found that Th17 cells and IL-17A are also increased in Hashimoto's thyroiditis (HT) patients and positively correlated with the titers of the TPOAb and TgAb thyroid autoimmune injury markers." (PMID 36643586, 2023). "The expression of Notch signaling pathway components was upregulated in EAT mice, but blockade of the Notch signaling pathway alleviated the degree of thyroiditis, decreased the Th17 cell proportions, and downregulated the IL-17A effector cytokine both in vivo and in vitro." (PMID 36643586, 2023). "Thus, the role of IL-17A+ T cells and IL-17A in ICI-induced thyroid disease and other irAEs needs to be further evaluated in additional mouse models and in humans." (PMID 37445704, 2023). "Subsequent investigation revealed increased IL17A+ T cells in secondary lymphoid tissues of combined anti-PD-1 and anti-CTLA-4 treated mice compared with isotype control, suggesting that cytokine production from RORγ+ Th17 and Tc17 was associated with thyroiditis." (PMID 39247203, 2024). "Recent studies in animal models have demonstrated that inhibiting IL-17A can reduce the severity of ICI-induced thyroiditis without compromising the antitumor efficacy of ICIs." (PMID 40535343, 2025). "Consecutive treatment with ixekizumab (IL-17A inhibitor) controlled PsA and did not induce a relapse of thyroiditis." (PMID 36902323, 2023).
chronic hepatitis B (21 papers, 2011 to 2024). "We have reviewed lots of clinical studies about IL-17A expression in peripheral blood and liver of patients with chronic hepatitis B (CHB)." (PMID 35144643, 2022). "Levels of the pro-inflammatory cytokine interleukin-17A (IL-17A) were found to be elevated in both the peripheral blood and liver in chronic hepatitis B (CHB) patients." (PMID 35144643, 2022). "IL-17A can also significantly stimulate monocytes and DCs to express their ligand (IL-17R) and produce pro-inflammatory cytokines such as IL-1β, TNF-α, IL-6, etc., which are important for liver damage during progression of chronic hepatitis B." (PMID 33435966, 2021).
colorectal tumors (21 papers, 2013 to 2024). "In the AOM-DSS-induced CAC mouse model, IL-17A plays a crucial role in the progression of colorectal tumors." (PMID 39906741, 2024). "In this study, we show that IL-17A is mainly secreted by γδT cells in the immune microenvironment of colorectal tumours." (PMID 37211606, 2023). "IL-17A, as a cytokine mainly secreted by γδT cells in the colorectal tumour immune microenvironment, can regulate the tumour microenvironment in multiple ways." (PMID 37211606, 2023). "A study has shown that Interleukin-17A (IL-17A), a pro-inflammatory cytokine primarily secreted by γδT cells in the immune microenvironment of colorectal tumors, can enhance intracellular reactive oxygen species (ROS) accumulation by disrupting mitochondrial function." (PMID 38987821, 2024). "VEGF signaling has been identified as a key factor in the pathogenesis of sporadic colorectal tumors in mouse and man, and both PGE2 and IL-17A are known to induce VEGF." (PMID 25839161, 2015). "Based on this backdrop, our present study revealed that colorectal tumors respond to FOFOX therapy by stimulation of supporting CAFs in the tumor-microenvironment to provide cues in the form of secreted factors (PN and IL17A) to stimulate WNT3A signals to maintain CICs." (PMID 35982950, 2022).
Immunodeficiency (21 papers, 2007 to 2025). Failure of the immune system to protect the body adequately from infection, due to the absence or insufficiency of some component process or substance. "Overall, these data suggest that both IFNγ and IL-17A were required for complete host protection and pulmonary containment of the WT strain in C. neoformans Δsgl1-vaccinated mice regardless of T cell immunodeficiency." (PMID 36229573, 2022). "The immunodeficiency of patients living with HIV leads to the limited production of inflammatory factors, and after treatment, IL-17a, the only inflammatory factor that increased, also dropped significantly, this might lead to further containment of tissue damage." (PMID 36407473, 2022). "Despite having slightly larger lesion sizes and bacterial burden during infection, CGD mice did not have significant differences in their mRNA levels for IL-1ß, IL-6, or IL-17A, consistent with their immunodeficiency reflecting a defect in neutrophil function rather than cytokine production." (PMID 25909449, 2015).
keloid (21 papers, 2009 to 2025). An irregularly shaped, elevated mark on the skin caused by deposits of excessive amounts of collagen during wound healing. "Further functional studies revealed that Th17 cells promote the proliferation, collagen expression, and migration of keloid fibroblasts by secreting IL-17A." (PMID 39872534, 2024). "Illustrating the downstream signaling pathways activated by IL-17A in fibroblasts of keloids can supply new targets for keloid therapy." (PMID 39872534, 2024). "The IF staining results showed that the proportion of IL-17A+/CD4+ cells was higher in keloids than in the normal controls." (PMID 39872534, 2024). "The mechanism by which IL-17A facilitates fibrosis in keloids is still unclear." (PMID 39872534, 2024). "Functional studies suggested that the supernatant of Th17 cells could promote proliferation, collagen expression, and migration of keloid fibroblasts through interleukin 17A." (PMID 39872534, 2024). "IL-17A, TNFAIP3, and CCL20 were found to be significantly increased in the keloid Th17 cells compared to the healthy skin Th17 cells." (PMID 39872534, 2024). "TGF-β works in tandem with IL17A to stimulate IL-6 and CCL2 production in fibroblasts, which are macrophage chemokines and offer a way for macrophages to be recruited to the keloid microenvironment." (PMID 37895153, 2023). "In addition, the factors related to Th1, Th2, and Th17 cells such as IL4/IL13, IL17A/IL22, ADAM33, IFN-γwere upregulated overall in keloid and AD." (PMID 38476235, 2024).
abortion (20 papers, 2014 to 2025). the ending of pregnancy by removing a fetus or embryo before it can survive outside the uterus. "They found IFN-γ, TNF-α, IL-2, IL-6 and IL-17A cytokines were significantly increased in spontaneous abortion ((SA) group and recurrent miscarriage (RM) group (Ctinfected) versus controls." (PMID 35392343, 2021). "However, the percentages of Th2 (p = 0.00001) and Th17/Th2 (producing IL-4 plus IL-17A, IL-17F and IL-22) (p = 0.001) T cell clones were significantly higher in the decidua of normal pregnancy compared to decidua of women suffering from unexplained recurrent abortion." (PMID 26798325, 2016). "The proportion of both Th17 cells and IL-17A concentrations was significantly higher in patients with unexplained recurrent spontaneous abortion (URSA) than in normal early pregnant (NEP) and non-pregnant (NP) patients." (PMID 24325348, 2014).
acute myeloid leukemia (20 papers, 2013 to 2025). Acute myeloid leukemia (AML) is a group of neoplasms arising from precursor cells committed to the myeloid cell-line differentiation. "In the present study, we wanted to find out whether polymorphic variants of the genes coding for IL-17A, IL-17F and receptor for IL-23 (as hallmarks of Th17 cells) could be associated with susceptibility to acute myeloid leukemia, disease progression and/or response to therapy." (PMID 24793548, 2014).
Airway obstruction (20 papers, 2006 to 2026). Obstruction of conducting airways of the lung. "Our population‐based cohort study links VOCs‐expanded LYM to elevated obstructive lung disease risk, with exposed individuals showing higher IL‐6 and IL‐17A levels." (PMID 41190786, 2026). "Accordingly, interior decorative VOCs‐associated obstructive lung diseases were potentially mediated by the elevation of LYM and regulated by IL‐6 and IL‐17A." (PMID 41190786, 2026). "Moreover, the cohort study associates VOCs‐expanded lymphocytes with increased risks of obstructive lung diseases, where exposed individuals show elevated IL‐6 and IL‐17A levels, correlating with VOC concentrations and lymphocyte proportions." (PMID 41190786, 2026). "We believe our study may help to understand the role of TSLP, IL-33, and IL-17A in a positive feedback loop between the airway epithelium and inflammatory cells infiltrating the airways in obstructive lung diseases." (PMID 32842623, 2020). "In addition, IL-17A can act with IL-6 to induce MUC5AC, and PM excessively regulates the expression of MUC5AC, causing excessive mucus production in the airways and exacerbating airway obstruction." (PMID 35837279, 2022). "Moreover, it is worth noting that IL-1, IL-8, and IL17A all play important roles in smooth muscle contraction and contribute to the impaired elasticity of the pulmonary tissues through bronchio/alveolar constriction, likely resulting in the increased tachypnea and airway obstruction." (PMID 30984178, 2019). "MUC5AC, the major glycoprotein component of mucus encoded by the conserved muc5ac gene, is expressed in airway epithelial cells and mediates IL-17A-induced mucus cell hyperplasia and mucus production via STAT3 signaling, thereby contributing to airway obstruction and inflammation." (PMID 41304567, 2025). "Additionally, IL-17A and IL-17 F stimulate airway epithelial and smooth muscle cells to produce mucins (MUC5B and MUC5AC), enhancing mucus hypersecretion and contributing to airway obstruction." (PMID 39850030, 2024). "The numbers of IL-17A+ cells and RANKL+ cells were increased, and significantly higher in COPD compared with never-smoker subjects or smoker subjects without airway obstruction (P<0.05)." (PMID 33613513, 2020).